TASP1 (taspase 1)
Description:
Protease responsible for KMT2A/MLL1 processing and activation. It also activates KMT2D/MLL2 (By similarity). Through substrate activation, it controls the expression of HOXA genes, and the expression of key cell cycle regulators including CCNA1, CCNB1, CCNE1 and CDKN2A (By similarity).
Synonyms: C20orf13; FLJ20212; dJ585I14.2; SULEHS
Tractability: Small molecule: it has a high-quality binding pocket. Antibody: the Human Protein Atlas places it where antibodies can reach. PROTAC: ubiquitination databases record sites on it; a small molecule that binds it is known.
Target class: Threonine protease T2 family; Threonine protease PBT clan; Enzyme; Threonine protease; Protease
Gene: Protein-coding gene on chromosome 20 (13,388,891 to 13,638,946, reverse strand). Ensembl gene ENSG00000089123.
Subcellular location (Human Protein Atlas): Plasma membrane
Pathways (Reactome):
Gene expression (Transcription): Formation of WDR5-containing histone-modifying complexes
Gene Ontology:
Molecular function: identical protein binding; threonine-type endopeptidase activity; hydrolase activity
Biological process: positive regulation of DNA-templated transcription; proteolysis; protein maturation
Cellular component: cytoplasm; cytosol
Genetic constraint (gnomAD): Loss-of-function variants: 12 observed, 37.53 expected, observed/expected ratio (o/e) 0.32, 90% interval 0.2 to 0.52. The upper end of that interval is the gene's LOEUF score, 0.52, which puts it in group 2 of 6, group 1 being the genes least tolerant of losing a copy. Missense variants: 298 observed, 398.46 expected, observed/expected ratio (o/e) 0.75, 90% interval 0.68 to 0.82. Synonymous variants: 137 observed, 147.77 expected, observed/expected ratio (o/e) 0.93, 90% interval 0.81 to 1.07.
Homologues: Orthologues: chimpanzee TASP1 (99% identical), macaque TASP1 (99% identical), pig TASP1 (98% identical), dog TASP1 (96% identical), guinea pig TASP1 (95% identical), mouse Tasp1 (95% identical), rabbit TASP1 (87% identical), rat Tasp1 (86% identical), tropical clawed frog tasp1 (79% identical), zebrafish tasp1 (73% identical), Drosophila melanogaster Tasp1 (37% identical), Caenorhabditis elegans tasp-1 (23% identical). Paralogues in human: ASRGL1 (28% identical), AGA (20% identical).
Diseases named in the same sentence as TASP1 in open-access papers:
TASP1 is named in the same sentence as 32 diseases in open-access papers, as found by Europe PMC text mining. Sharing a sentence is not in itself a finding about the gene and the disease. The quoted sentences say what the papers report.
leukemia (7 papers, 2011 to 2025). A malignant (clonal) hematologic disorder, involving hematopoietic stem cells and characterized by the presence of primitive or atypical myeloid or lymphoid cells in the bone marrow and the blood. "Aberrant expression of TASP1 has been found in leukaemia and alters cell cycle progression, cell proliferation and apoptosis." (PMID 34197029, 2021). "Considering the vital role of TASP1 in leukaemia, the potential function of circTASP1 in the prognosis of AML needs to be investigated." (PMID 34197029, 2021).
brain cancer (3 papers, 2016 to 2021). A primary or metastatic malignant neoplasm affecting the brain. "Aberrant expression of TASP1 has been found in numerous liquid and solid malignancies, including leukaemia, breast cancer, lung cancer, head and neck cancer, brain cancer, colon cancer, glioblastoma and melanoma 19, 25-28." (PMID 32071545, 2020). "Similarly, previous studies showed that TASP1 was also increased in brain cancer, breast cancer, colon cancer, head and neck squamous cell carcinoma, and blood cancer." (PMID 34012990, 2021).
breast carcinoma (3 papers, 2016 to 2023). "TASP1 (a threonine protease) plays an essential role in both normal mammary gland development and breast cancer progression." (PMID 36993976, 2023). "In previous studies, Dong found that TASP1 promotes the proliferation of breast cancer cells." (PMID 34012990, 2021). "Mixed-lineage leukaemia has been identified as a major substrate of TASP1 and is required for the development of HER2-positive breast cancer in vitro." (PMID 36993976, 2023).
gallbladder cancer (3 papers, 2020 to 2022). "Taspase 1 (TASP1) promotes the proliferation and migration of gallbladder cancer cells by targeting the upregulation of FAM49B through the TASP1-PI3K/Akt-FAM49B axis." (PMID 36499755, 2022). "Zhang found that TASP1 promoted gallbladder cancer proliferation and migration." (PMID 34012990, 2021).
colon cancer (2 papers, 2010 to 2021). "DNA sequence analyses using primers flanking the coding sites for taspase 1 cleavage site in the MLL2 gene revealed no alterations in the colonic cancer cell lines carrying MLL2FL (data not shown)." (PMID 20433758, 2010).
adenoma (1 paper, 2024). A neoplasm arising from the epithelium. "Some MP-RNAs interacted with much more partners in adenoma and cancer tissues than in paracancer tissues, such as SLC16A14, POLA2, PCDH11X, TASP1, TSPY20P." (PMID 38773399, 2024).
Cholecystitis (1 paper, 2020). The presence of inflammatory changes in the gallbladder. "The protein expression level of TASP1 was significantly increased in 72 GBC tissues as compared with the 60 cholecystitis tissues." (PMID 32071545, 2020).
cryptorchidism (1 paper, 2022). The failure of one or both testes of a male fetus to descend from the abdomen into the scrotum during the late part of pregnancy. "However, despite the fact that cryptorchidism has been reported in some WDSTS patients, it has never been associated with KMT2A mutations; instead, it has been associated with TASP1, which is a regulator of KMT2A." (PMID 35893049, 2022).
gallbladder tumor (1 paper, 2020). "To determine the effect of TASP1 on gallbladder tumor progression in vivo, we performed xenograft tumor assays using TASP1-depleted GBC-SD cells." (PMID 32071545, 2020). "Furthermore, we assessed TASP1 expression levels in the gallbladder tumor and non-tumor tissues by IHC staining." (PMID 32071545, 2020).
gastric cancer (1 paper, 2021). A primary or metastatic malignant neoplasm involving the stomach. "However, the regulatory mechanism of TASP1 in gastric cancer (GC) remains unclear." (PMID 34012990, 2021).
gastric tumor (1 paper, 2021). "The gastric tumor slides were made to do the IHC staining of the TASP1." (PMID 34012990, 2021).
hepatocellular carcinoma (1 paper, 2017). A malignant tumor that arises from hepatocytes. "For example, CTBP1 is listed by Cancer Resource, and TASP1 is also a drug target, which is used to combat novel diseases whose candidate genes are targeted by HNF4alpha splice variants in hepatocellular carcinomas, as well as PNKP and RAG2." (PMID 28691014, 2017).
Infertility (1 paper, 2022). "TASP1 cleaves general transcription factor TFIIAα−β to enable testis-specific transcription; Tasp1-null male mice were unable to activate spermatogenic gene activation, which lead to the release of immature germ cells and infertility." (PMID 35600599, 2022).
microphthalmia (1 paper, 2024). Congenital or developmental anomaly in which the eyeballs are abnormally small. "Interestingly, reduced expression of Cdkn2a in TASP1-deficient mice significantly decreased cranial and ocular malformations, including microphthalmia, suggesting inhibition of these genes may be required for correct retinal progenitor proliferation to drive ocular morphogenesis." (PMID 38821055, 2024).
microtia (1 paper, 2024). "The verification of the multi-omics results with other microtia patients identified that ALDOB, ADIPOQ, CDH13 and TASP1, and oxidative stress may play a role in chondrogenic anomalies." (PMID 38802922, 2024).
prostate carcinoma (1 paper, 2020). A carcinoma that arises from epithelial cells of the prostate gland. "Although PI3K signaling increases MLL1 cleavage by TASP1 and MLL1 activity in prostate cancer, we determined that TASP1 regulated FAM49B expression through PI3K/AKT signaling pathway in GBC cell lines." (PMID 32071545, 2020).
Stroke (1 paper, 2021). Sudden impairment of blood flow to a part of the brain due to occlusion or rupture of an artery to the brain. "In addition, circ_Dlgap3_1, circ_Tasp1_7, circ_Herc3_2, and circ_Chd2_24 targeted the antiapoptotic protein, Bcl-2, as well as apoptotic protease activating factor 1, supporting their participation in the apoptotic process after stroke." (PMID 34868302, 2021).
Suleiman-El-Hattab syndrome (1 paper, 2024). "Loss-of-function variants of TASP1 can lead to Suleiman-El-Hattab syndrome (SULEHS), a disorder affecting histone modification." (PMID 38311789, 2024).
type 1 diabetes (1 paper, 2020). "We identified one novel region, 20p12.1 (TASP1; genome-wide P < 5 × 10–8) and three regions, 1q21.3 (MRPS21–PRPF3), 2p25.2 (NRIR), 3q22.1 (COL6A6), with suggestive evidence of association (P < 8.5 × 10–8) with progression from islet autoimmunity to type 1 diabetes." (PMID 33154504, 2020).
cancer (10 papers, 2011 to 2026). A tumor composed of atypical neoplastic, often pleomorphic cells that invade other tissues. "The model identified key genes such as C3orf36, JHY, and TASP1, showing significant differences in mutation counts across cancers." (PMID 41870130, 2026). "Indeed, loss of taspase 1 has been shown previously to impede cancer cell proliferation and tumor progression in breast cancer." (PMID 32450905, 2020). "At first glance, our data seemingly conflict with prior findings, namely that the cleavage of Myo1f by the cancer-promoting Tasp1 prevents Myo1f-induced filopodia formation, which would admittedly avert the acceleration of metastatic processes." (PMID 35601920, 2022). "Threonine aspartase 1 (TASP1) was reported to function in the development of cancer." (PMID 34012990, 2021). "Previous studies found that TASP1 was highly expressed in cancer cells, and TASP1 downregulation could promote the apoptosis and inhibit the proliferation of cancer cells." (PMID 34012990, 2021). "Whether this signaling pathway is located at the downstream of TASP1 may be based on the cancer type and tissue specificity." (PMID 32071545, 2020). "Threonine aspartase 1 (TASP1), a particularly conserved protease that cleaves mixed lineage leukemia 1 (MLL), regulates the expression of homeotic genes and is involved in the occurrence of cancer." (PMID 34012990, 2021). "TASP1 is not a traditional oncogene, but it can help the occurrence of cancer by cleaving MLL and TFIIA and be a potential anticancer drug target." (PMID 34012990, 2021). "Although TASP1 has been found in various cancers and was characterized as a 'non-oncogene addiction' protease, our knowledge on its detailed functions and the underlying mechanisms contributing to cancer is still incomplete." (PMID 32071545, 2020).
tumor (7 papers, 2010 to 2025). "Here, we introduce a light-responsive supramolecular ligand system designed to modulate Taspase 1, a protease critical for embryogenesis and implicated in tumor progression." (PMID 40932873, 2025). "Here we observed that TASP1 levels were substantially overexpressed in GBC samples compared with non-tumor tissues." (PMID 32071545, 2020). "Second, TASP1 depletion effectively inhibits cell proliferation and metastasis in vitro, and markedly suppresses tumor growth in vivo." (PMID 32071545, 2020). "We found that the tumor volume and weight of TASP1-depleted xenografts were significantly inhibited." (PMID 32071545, 2020). "Furthermore, the expression of the TASP1 protein in tumor tissues of 20 patients was higher than that in normal tissues." (PMID 34012990, 2021). "This uncleaved MLL2FL observed in the cytoplasmic and nuclear fractions of the advanced tumor cell lines could be a consequence of insufficient endogenous taspase 1 required for processing the excess MLL2." (PMID 20433758, 2010). "The TASP1 and FAM49B mRNA levels has a significant positively correlation in tumor specimens by Pearson correlation analysis (R = 0.6180, P < 0.001)." (PMID 32071545, 2020). "Consistent with the tumor tissue profiles, the GBC cells expressed higher levels of TASP1 than that in normal cell." (PMID 32071545, 2020). "To explore the pathological role of TASP1 in GBC development, we examined the TASP1 mRNA levels in 72 pairs of GBCs and found that the TASP1 expression was higher in tumor tissues compared with their corresponding adjacent non-malignant tissues (P = 0.0026)." (PMID 32071545, 2020).
TASP1 also shares sentences with these, for which no sentence is quoted: acute monocytic leukemia (1 paper); anemia (1); blood cancer (1); childhood leukemia (1); developmental delay (1); head and neck cancer (1); head and neck squamous cell carcinoma (1); head and neck tumours (1); intellectual disability syndrome (1); melanoma (1); respiratory infections (1).